TNF (tumor necrosis factor)
Diseases named in the same sentence as TNF in open-access papers (continued):
Sharing a sentence is not in itself a finding about the gene and the disease.
tumor (continued). "Addition of miR-28 mimics increase the level of IL-2 and TNF-α of T cells, suggesting another benefit of miR-28 that may restore the cytokine secretion function of exhausted T cells in tumor." (PMID 27447564, 2016). "Using the fruit fly as a cancer model, Marcos demonstrated that the genetic composition of a tumor is a key determinant as to whether tumor necrosis factor (TNF) acts as a tumor-suppressing or tumor-promoting factor." (PMID 26758990, 2016). "TNFα has a tumor-promoting role, and TNFα expression generally increases with tumor stage." (PMID 26918940, 2016). "Expression of inflammatory cytokines, such as TNF-α, was detected at the tumor site." (PMID 26951080, 2016). "Our previous study has demonstrated that low dose TCP-1/TNFα could normalize tumor blood vessel, enhance the intratumoral accumulation of anticancer drug 5-FU, thus potentiating its antitumor activity." (PMID 27342639, 2016). "Blockage of PD-L1 expression on tumor cells might activate tumor-specific T cell to kill tumor cells by mediating tumor necrosis factor alpha (TNF-α) and interferon gamma (IFN-γ)." (PMID 26771840, 2016). "Moreover, serum levels of IFN-γ and TNF-α were markedly elevated by ascophyllan treatment in the tumor-bearing mice." (PMID 27008707, 2016). "TNF-α is known to play an important role in various aspects of tumor progression." (PMID 27042827, 2016). "As jacalin-activated macrophages produced high amounts of proinflammatory mediators like TNF-α, we investigated whether the supernatant from these cells has a cytotoxic effect on tumor cell lines." (PMID 27119077, 2016). "M1 macrophages can be activated by Th1 cytokine interferon γ (IFNγ) and microbial products, and they express high levels of pro-inflammatory cytokines (e.g. TNFα, IL-1, IL-6, IL-12 and IL-23), and inducible nitric oxide synthase (iNOS), and are capable of killing pathogens and tumor cells." (PMID 26799669, 2016). "Intratumoral administration of IFN-α2, IFN-γ, TNF-α, and IL-2 significantly enhanced the anti-tumor effect of ovalbumin-specific CD8+ T-cell (OT-I) therapy, whereas GM-CSF increased tumor growth in association with an increase in immunosuppressive cell populations." (PMID 26107883, 2015). "Moreover, the mechanisms by which down-regulation of A20 inhibited tumor growth was that si-A20 induced the apoptosis of MDSCs in the presence of TNF-α through activating JNK pathway." (PMID 26561336, 2015). "Serum MCP-1 levels were also lower in tumor-bearing TNFα−/− mice." (PMID 26167165, 2015). "Other cytokines produced by NK cells, e.g., TNF-α, GM-CSF, IL-10, and IL-13, may be considered for the evaluation of tumor cell sensitivity to NK cell-mediated killing and could be significant predictive markers for therapy effectiveness." (PMID 25674087, 2015). "Thus, VEGF and TNF-α in the tumor mass were more pronounced when 4T1 cells were inoculated in 10-day old implants when compared with the same features of tumors grown in 24h implants." (PMID 26158775, 2015). "Furthermore, tumour-derived factors, including GM-CSF and TNF-α, contributed to PD-L1 expression on neutrophils in patients with HCC." (PMID 26581194, 2015). "M2 macrophages promote tumor progression by enhancing angiogenesis and inhibiting an immune response against tumors, whereas M1 macrophages promote a proinflammatory microenvironment by releasing IL-1β, IL-6, IL-12, and tumor necrosis factor alpha (TNF-α)." (PMID 26131447, 2015). "Tumor regression in a mouse A431 xenograft model after intravenous administration of lactoferrin- and lactoferricin-bearing diaminobutyric polypropylenimine (DAB) dendriplex encoding tumor necrosis factor (TNF) α." (PMID 25933695, 2015). "Treatment of OSCSCs with supernatants from IL-2 + anti-CD16mAb + sAJ2 in the presence of anti-TNF-α had slight enhancing effect on tumor growth, whereas supernatants obtained from anti-IFN-γ in combination with IL-2 + anti-CD16mAb + sAJ2-treated NK cells enhanced tumor cell growth substantially." (PMID 26697005, 2015).
tumor (continued). "TNFα and NO, as well as other mediators secreted by tumor inflammatoryinfiltrate, mainly macrophages and myeloid cells, have been reported to exertcontrasting effects on tumor cells." (PMID 25659093, 2015). "Tumor samples displayed increased TNF-α levels (239.8 ± 13.07 pg/mL of homogenate in adjacent breast and 418.1 ± 19.6 pg/mL of homogenate in tumoral tissue, p < 0.001) and NO (4.64 ± 0.32 μM/mg tissue in adjacent breast and 6.89 ± 0.32 μM/mg tissue in tumoral tissue, p < 0.001)." (PMID 26697139, 2015). "Significantly, silibinin suppressed intra-tumorally injected TNF-α-induced tumor growth." (PMID 26142316, 2015). "Via NF-κB, TNF-α is also central to the interactions between tumor cells and macrophages that result in not only increased invasive capacity of malignant cells, but also in the switch to an alternative tumor-promoting phenotype." (PMID 26418748, 2015). "TNF-α was also demonstrated to be a key inducer of inflammatory characteristics in MSCs, with activities that were much more pronounced and general than those induced by tumor constituents (Tumor CM)." (PMID 25928089, 2015). "Another group reported that an IAP antagonist could activate NF-κB signaling and induce TNFα production to kill tumor cells." (PMID 25575821, 2015). "In tumor microenvironments, MSCs can be activated by pro-inflammatory cytokines IFN-γ, TNF-α, or IL-1β, which are secreted by tumor cells and macrophages and then produce immunomodulatory molecules, such as IDO, PGE2, IL-6, IL-10, HLA-G5, and nitric oxide (NO)." (PMID 26694366, 2015). "Bglap is regarded as a TNF-α target and indirectly suggests a tumor-promoting function in cancers." (PMID 26266941, 2015). "However, the expression of endogenous TNF resists the cytotoxicity of exogenous TNF to kill tumor cells." (PMID 26108796, 2015). "It has been shown that TNF-α could act as endogenous pro motor of tumour via activation of NF-kB transcriptional factor." (PMID 25858079, 2015). "However, chronic inflammation was more effective than acute inflammation in inducing VEGF and TNF-α and tumor progression." (PMID 26158775, 2015). "At the tumor site, TNF-α can induce direct release of VEGF from the neutrophils." (PMID 26770016, 2015). "Overall, a coordinated inflammatory network may be established at the tumor site between the cancer cells and stromal cells, set up by inflammatory cytokines such as TNF-α and IL-1β." (PMID 25928089, 2015). "Additionally, numerous soluble mediators, including TNF-α, TGF-α, TGF-β, IL-1β, IL-1α, IL-6, IL-8, VEGF, and others have been implicated in PC carcinogenesis, tumor progression, and treatment resistance." (PMID 26498838, 2015). "However, the circulating levels of TNF-α were higher in implant-bearing tumor animals than in those of the animals bearing tumor alone." (PMID 26158775, 2015). "Furthermore, Th1-derived IFN-γ/TNF-α are critically important for tumor rejection in preclinical models and synergistically induce apoptosis of tumor cells in vitro." (PMID 26082780, 2015). "In addition, other cytokines like Tumor Necrosis Factor-α (TNF-α), secreted by activated T lymphocytes or macrophages, can be induced at the tumor site." (PMID 25853464, 2015). "However, heightened levels of IL-6 and TNF-α were observed in supernatants of human PBACs incubated with hCG-primed tumor conditioned medium." (PMID 26608647, 2015). "Previous studies also suggested that TNF-α produced by macrophages is a key mediator for inflammation and might promote β-catenin activity in tumor cells." (PMID 26226629, 2015). "TNF-α, as its name connotes, has the ability to kill tumor cells." (PMID 28536409, 2015). "In contrast, low, sustained TNF-α production levels can induce a tumour phenotype." (PMID 26508818, 2015). "Our study suggests that higher constitutive TNF-α expression in patients with TNBC rather than other BC subtypes is associated with distant tumour metastasis." (PMID 26165253, 2015).
tumor (continued). "The regulation of TNF-Rs is critical to governing the responsiveness of tumor cells to TNF-α." (PMID 25624918, 2015). "Our previous data indicated that the presence of cytotoxic CD8+ T cells is an important factor responsible for the eradication of AB1-GAG by releasing inflammatory IFN-γ and TNF-α in the vicinity of target cells as well as by initiating TRAIL-directed tumor cell apoptosis." (PMID 26431275, 2015). "In our model, a2NTD treatment stimulates neutrophils to secrete enhanced amount of TNFα, IL-1 and IL-6 suggesting that neutrophils in the site of the tumor may be a potential source of these mediators." (PMID 26460736, 2015). "Similarly, irradiated tumor cells inhibited the activation of LPS-stimulated DCs through a decrease in surface maturation ligands and inflammatory IL-12 and TNF-α cytokine production." (PMID 27551446, 2015). "To determine how tumor-infiltrating myeloid cells could contribute to tumor regression, we first looked at the production of TNFα by myeloid cells." (PMID 26337837, 2015). "Cancer pain can be caused by different mediators: immune system cells infiltrating the tumor: neutrophils, T cells, and macrophages secrete prostaglandins, endothelin, TNF-α, Transforming Growth Factor (TGF), IL-1 and IL-6, Epidermal Growth Factor (EGF), and Platelet Derived Growth Factor (PDGF)." (PMID 26538839, 2015). "The elaborate cross-talk between macrophages, MDSCs, and tumor cells result in differential production of IL-6, IL-10, TNF-α, and NO, suggesting that the interaction between these cells has the potential to significantly alter the inflammatory milieu within the tumor microenvironment." (PMID 26052505, 2015). "TNF-α is not only a chemoattractant for immune cells that facilitate tumor cell clearance but also a strong inducer of extrinsic apoptosis and necroptosis in tumor cells." (PMID 26307977, 2015). "Other reports showed that paracrine signaling derived from the microenvironment also has an important role in NF-κB activation in cancer cells and TNFα produced by myeloid cells, particularly macrophages, can promote tumor growth in vivo and stimulate tumor cell invasion in vitro." (PMID 27462428, 2015). "Chronic inflammation may promote tumorigenesis, and TNF has been demonstrated to both promote and inhibit tumour development in animal models depending on dose and biological conditions." (PMID 26481039, 2015). "In addition, overall platinum content in tumours was increased 24 h after treatment with TNF-α compared to tumours treated with CDDP alone indicating facilitated uptake of CDDP in TNF-α treated tumours." (PMID 25810699, 2015). "MyD88-deficiency in macrophages reduced MCP-1 expression and production by LLC cells in vitro, but MyD88-deficiency did not reduce serum MCP-1 levels or LLC tumor volumes as effectively as TNFα-deficiency in vivo." (PMID 26167165, 2015). "Here, we show that the secretion of TNF-α and IL-1β by tumor-bearing dogs is gradually decreased after administration of pardaxin, implying that pardaxin may induce tumor cell apoptosis at dog tumor sites." (PMID 25544775, 2015). "Notably, in vivo tumor xenograft study revealed that silibinin was also able to reduce the size of the tumors formed by HCT116 cells alone or those treated with TNF-α." (PMID 26142316, 2015). "TNF-α, however, has been reported to have both pro- and anti-tumour effects." (PMID 26407999, 2015). "Based on these results, we speculate that the mechanism of action of adjuvant TNF-α in electrochemotherapy treated tumours is primarily through a vascular action." (PMID 25810699, 2015). "We first evaluated the role of FAT10 in modulating TNF-α induced tumor growth." (PMID 26142316, 2015). "Since, in the tumor microenvironment, tumor infiltrating lymphocytes (TILs) encounter tumor antigens and undergo activation, we thought that it will be physiologically more relevant to study the potential role of TNF-α using 7-day activated T cells." (PMID 26226135, 2015).
tumor (continued). "In sharp contrast to what we observed in mice lacking either TNF or TNF-R1, the tumor growth of B16K1 cells was not impaired in FAN-deficient mice as compared to their wild-type counterparts (Montfort and Ségui, unpublished data)." (PMID 26622939, 2015). "This prevented us from analyzing the immune cell content of the treated tumors, but we propose that the overall anti-tumor effect seen in this group was due to the direct anti-tumor effects of TNF-α on one hand and immunological synergy with T-cell therapy on the other." (PMID 26107883, 2015). "The objective of this study was to determine the in vitro tumor-inhibitory effect of a recombinant adenovirus expressing a fusion protein of tumor necrosis factor (TNF) related apoptosis inducing ligand (TRAIL) and hemagglutinin-neuraminidase (HN) genes on the MSB-1 Marek’s disease tumor cell line." (PMID 25729329, 2015). "TNF-α has been shown to mediate tumor initiation, promotion, and metastasis." (PMID 25665066, 2015). "It is interesting to note that the in vitro enhancement of LPS-induced IL-6 and TNFα production seemed to be a transient effect which faded over 72 h, although peritoneal macrophages from 4T1 tumor-bearing mice also exhibited increased production of pro-inflammatory cytokines." (PMID 26177198, 2015). "While the secretion of these cytokines from the primary tumor undoubtedly plays a role in metastatic progression, our observations strongly suggest that priming of distal macrophages can result in secondary production of TNFα, IL-6, and CCL2." (PMID 26177198, 2015). "Different tumour cells produce TNF-α, including ovarian cancer and breast cancer." (PMID 25858079, 2015). "In particular, proinflammatory cytokines, IL-1β, IL-6, and TNF-α may be released as part of the host response to the tumor or in response to tissue damage or depletion of immune cell subsets associated with cancer treatment." (PMID 25945105, 2015). "In the current study we provide new findings on the networks that control the inflammatory phenotype of CAFs and MSCs, demonstrating key roles for the inflammatory cytokines TNF-α and IL-1β in upregulating the release of inflammatory, tumor-promoting chemokines by these two cell types." (PMID 25928089, 2015). "Furthermore, the production of high levels of IL-10 and transforming growth factor-β1 (TGF-β1) by malignant cells reduces ovarian production of interferon-γ (IFN-γ) and TNF-α, suppressing the immune response against the tumor cells." (PMID 25624918, 2015). "Though named for this tumor-killing activity, in the event the peptide TNF proved to be as pleiotropic as any cytokine, being very widely distributed across biology, important in physiology, and in excess incriminated in innate immunity and disease pathogenesis." (PMID 26221543, 2015). "The failure to respond to immunotherapy was due to the inability of monocyte-derived cells in the tumour microenvironment to produce pro-inflammatory cytokines (e.g., TNF and IL-12) in response to CpG and the subsequent necrosis needed to induce tumour regression." (PMID 28936244, 2015). "Inaddition, λ-carrageenan could enhance the secretion of IL17A in spleen andsignificantly increase the level of TNF-α in tumor, most of which wassecreted by infiltrating macrophages." (PMID 26098663, 2015). "TNFα, whose expression is reduced in p38γ/δ−/− mice, is involved in the progression of different tumours, including chemically induced squamous cancers, and could then mediate the effects of p38γ/δ deletion." (PMID 26079427, 2015). "These transformation-encoding CNAs, together with deletion of TNF on 6p, and amplification of RAD51AP1 and ITPR2 on 12p, are correlated with a suppression of cell cycle arrest, senescence, and apoptosis, i.e., a tumor cell’s immortality, and a patient’s shorter survival time." (PMID 25875127, 2015).
tumor (continued). "A growing body of evidence in the literature indicates that TNF may behave as a tumorigenic cytokine, facilitating cancer cell immune escape and tumor progression." (PMID 26622939, 2015). "Inflammatory cells in the tumor microenvironment can produce TNFα." (PMID 25483835, 2015). "Reports indicated that TNF-α possesses both anti-tumor and pro-tumor activities." (PMID 26526388, 2015). "Since the TERT protein is proposed to co-activate NFκB to enhance gene-expression of e.g IL-6, TNFα and other pro-inflammatory cytokines, contributing to tumor progression, we analyzed the relative mRNA levels on thirty-six AML patients with different rs2853669 genotypes." (PMID 26298771, 2015). "Furthermore, we successfully demonstrated cetuximab-mediated tumor infiltrations and increased TNFα and IFN-γ secretions of sMICA-inhibited NK cells in associated HNSCC spheroids using 2D- and 3D-microscopy techniques." (PMID 26579120, 2015). "Specifically, the treatment of tumours before the electrochemotherapy was significantly more effective (p<0.05) than treatment with TNF-α after electrochemotherapy, producing longer tumour growth delay, and higher tumour curability rate (36% vs. 27%, respectively)." (PMID 25810699, 2015). "In our study, under TNF-α treatment, the number of the adhered tumor cells on the ECs monolayer decreased, which seemed to be contradictory regarding the enhanced metastatic behavior of the tumor cells." (PMID 26631692, 2015). "In a model with tumors induced by AOM and dextran sulfate sodium (DSS) in lean (C57BL6/J) and ob/ob mice, it was shown that when pathways involving TNFα were inhibited, tumor numbers and proliferation and apoptosis profiles were returned to levels observed in lean mice." (PMID 26347815, 2015). "Earlier studies demonstrated that activated macrophages could kill tumor cells, primarily via the secretion of TNF-α." (PMID 29061951, 2015). "In a hypothetical human patient whose tumor is treated with an OV based upon TPV, we hypothesize that the ablation of the 2L gene may result in an effective increase in TNF concentration at the tumor site, which may ultimately act to increase tumor clearance." (PMID 25887490, 2015). "TNF-α also functions as a growth factor for most tumor cells." (PMID 25665066, 2015). "Moreover, there was a high release of TNFα from both human macrophages and mouse tumor tissues in the Sal-YB1-treated group." (PMID 26286454, 2015). "Secretion of miR-21 from tumor-cell-derived exosomes or up-regulation of miR-21 in TAMs by tumor-derived pro-inflammatory products such as IL-6 or TNF, may participate in TAM reprograming and thereby facilitate growth, intravasation, and spread of tumor cells." (PMID 25688245, 2015). "Taken together, these results suggest that elevated levels of IL-21 in the tumors of Apcmin/+ mice support a tumor-promoting inflammatory microenvironment characterized by enhanced production of IL-17A, IL-22, TNF-α and IL-6 and hyper-activation of STAT3/NF-kB." (PMID 25839161, 2015). "Using different experimental approaches, we provide evidence that, at least in this model and in the EG7 model, not only T cells but also activated, cytotoxic, tumor infiltrating myeloid cells are required for eliminating the tumor by TNFα production and phagocytosis of tumor cells." (PMID 26337837, 2015). "Number of functional blood vessels was significantly reduced in tumours after treatment with TNF-α." (PMID 25810699, 2015). "Other studies have indicated a tumor-suppressive activity of MSC after preactivation with TNF-α." (PMID 24936198, 2014). "Indeed, there seem to be numerous contexts in which TNF-α signaling helps to initiate carcinogenesis and sustain tumor growth." (PMID 24672527, 2014). "The tumor-promoting feature of Th17 cells largely arises from secretion of large amounts of IL-17, which in turn induces expression of pro-inflammatory factors such as TNF-α, IL-6, IL-1, and iNOS, known to play a role in CRC pathogenesis." (PMID 24639678, 2014).